RIT1 (Ras like without CAAX 1)
Description:
Plays a crucial role in coupling nerve growth factor (NGF) stimulation to the activation of both EPHB2 and MAPK14 signaling pathways and in NGF-dependent neuronal differentiation. Involved in ELK1 transactivation through the Ras-MAPK signaling cascade that mediates a wide variety of cellular functions, including cell proliferation, survival, and differentiation. Recognized by LZTR1, which mediates its ubiquitination by a BCR (BTB-CUL3-RBX1) E3 ubiquitin-protein ligase complex.
Synonyms: RIBB; RIT; ROC1; MGC125864; MGC125865; NS8
Tractability: Small molecule: a structure with a bound ligand is known. Antibody: UniProt places it where antibodies can reach, with medium confidence; its Gene Ontology location is reachable by antibodies, with medium confidence. PROTAC: ubiquitination databases record sites on it; its protein half-life has been measured.
Gene: Protein-coding gene on chromosome 1 (155,897,808 to 155,911,408, reverse strand). Ensembl gene ENSG00000143622.
Subcellular location: Cell membrane
Pathways (Reactome):
Signal Transduction: Signalling to p38 via RIT and RIN
Gene Ontology:
Molecular function: GTP binding; GTPase activity; protein binding; calmodulin binding; G protein activity
Biological process: Ras protein signal transduction; signal transduction
Cellular component: plasma membrane; membrane
Genetic constraint (gnomAD): Loss-of-function variants: 5 observed, 20.12 expected, observed/expected ratio (o/e) 0.25, 90% interval 0.13 to 0.52. The upper end of that interval is the gene's LOEUF score, 0.52, which puts it in group 2 of 6, group 1 being the genes least tolerant of losing a copy. Missense variants: 195 observed, 261.46 expected, observed/expected ratio (o/e) 0.75, 90% interval 0.66 to 0.84. Synonymous variants: 69 observed, 86.31 expected, observed/expected ratio (o/e) 0.8, 90% interval 0.66 to 0.98.
Gene-disease validity (ClinGen):
ClinGen rates the evidence that RIT1 causes each of these diseases.
Noonan syndrome (autosomal dominant): Definitive. Noonan Syndrome (NS) is characterized by short stature, typical facial dysmorphism and congenital heart defects.
Homologues: Orthologues: chimpanzee RIT1 (100% identical), macaque RIT1 (100% identical), pig RIT1 (99% identical), guinea pig RIT1 (97% identical), dog RIT1 (97% identical), rabbit RIT1 (97% identical), mouse Rit1 (95% identical), rat Rit1 (95% identical), tropical clawed frog rit1 (76% identical), zebrafish rit1 (74% identical). Paralogues in human: RIT2 (66% identical), RRAS (47% identical), RRAS2 (46% identical), KRAS (42% identical), NRAS (42% identical), HRAS (41% identical), MRAS (41% identical), RAP1A (41% identical), RAP1B (41% identical), RALA (39% identical), RALB (39% identical), RAP2A (39% identical), and 23 more.
Diseases named in the same sentence as RIT1 in open-access papers:
RIT1 is named in the same sentence as 76 diseases in open-access papers, as found by Europe PMC text mining. Sharing a sentence is not in itself a finding about the gene and the disease. The quoted sentences say what the papers report.
Noonan syndrome (41 papers, 2016 to 2025). "We expressed RIT1P1, RIT1P2, RIT1P3, RIT1 wildtype (RIT1wt), and two recurrent RIT1 mutations found in Noonan syndrome (p.F82L and p.M90I)." (PMID 38969873, 2024). "All three delins variants are located close to the switch 2 domain of the RIT1 protein, a region that also harbors germline missense variants commonly associated with Noonan syndrome." (PMID 38969873, 2024). "All three somatic mutations are located close to the switch 2 domain of RIT1, a domain that also harbors RIT1 germline mutations commonly associated with Noonan syndrome." (PMID 38969873, 2024). "Activating RIT1 variants cause Noonan syndrome, a finding that supports distinct genetic causes and molecular pathophysiology in pediatric- and adult-onset HCM." (PMID 37767697, 2023). "Germline RIT1 variants cause Noonan syndrome (NS), a RASopathy characterized by craniofacial dysmorphism, short stature, and congenital heart disease." (PMID 37450595, 2023). "Rarely, variants in RIT1 gene have also been found to cause Noonan syndrome and RIT1 specifically has been associated with an increased incidence of hypertrophic cardiomyopathy and perinatal abnormalities including polyhydramnios." (PMID 36593444, 2023). "The case highlights the fact that despite its heterogeneous presentation, RIT1‐associated Noonan syndrome can be extremely severe with poor outcome." (PMID 32396283, 2020). "This case details a novel cardiac and hematologic phenotype and illustrates the severity of RIT1‐associated Noonan syndrome." (PMID 32396283, 2020). "Phenotypically, RIT1‐associated Noonan syndrome patients are found to have typical Noonan syndrome facies, milder growth retardation, but higher frequency of cardiac abnormalities when compared to other phenotypes." (PMID 32396283, 2020). "More importantly, RIT1‐associated Noonan syndrome has more complications and worse prognosis during the perinatal period." (PMID 32396283, 2020). "We present a patient with RIT1‐associated Noonan syndrome, who in addition to the congenital heart defect, had monocytosis, myeloproliferative disorder, and hemodynamically significant ventricular dysrhythmias that led to his demise." (PMID 32396283, 2020). "In this report, we present a patient with RIT1‐associated Noonan syndrome, who had pulmonary valve stenosis, monocytosis, myeloproliferative disorder, and hemodynamically significant ventricular dysrhythmias." (PMID 32396283, 2020). "We present a patient with RIT1‐associated Noonan syndrome, who in addition to the congenital heart defect, had monocytosis, myeloproliferative disorder, and accelerated idioventricular rhythm that was associated with severe hemodynamic instability." (PMID 32396283, 2020). "Including the patient in this report, this mutation has been reported in 18% (25/141) of patients with RIT1‐associated Noonan syndrome." (PMID 32396283, 2020). "Germline and somatic RIT1 mutations have been identified in Noonan syndrome (NS) and cancer, respectively." (PMID 29734338, 2018). "The recent identification of germline gain-of-function RIT1 mutations in patients with Noonan syndrome (NS) demonstrated the importance of this small GTPase for embryonic development." (PMID 29734338, 2018). "Our patient with the RIT1 mutation presented with typical facial features of Noonan syndrome, as well as hypertrophic cardiomyopathy (HCM) and sub-aortic stenosis." (PMID 29402968, 2018). "Germline mutations in RIT1 have also been identified in patients with Noonan syndrome." (PMID 41388936, 2025). "Regarding RIT1 gene variants associated with Noonan syndrome, multiple reports have documented their occurrence in fetuses with increased NT, hydrops fetalis, and other ultrasound features suggestive of Noonan syndrome." (PMID 41317105, 2025). "Also, on day 5 of admission, rWGS preliminary results returned identifying a likely pathogenic variant in RIT1, a rare cause of Noonan syndrome." (PMID 36593444, 2023).
Noonan syndrome (continued). "RIT1 heterozygous gain-of-function mutations causes Noonan syndrome 8 (OMIM: 615355)." (PMID 35806420, 2022). "RIT1 is one of the most recent genes identified in association with Noonan Syndrome." (PMID 32396283, 2020). "We report a case of neonatal Noonan syndrome associated with RIT1 mutation." (PMID 32396283, 2020). "In summary, we report a case of neonatal Noonan syndrome associated with RIT1 mutation." (PMID 32396283, 2020). "We hypothesize that RIT1 delins close to the switch 2 region led to a distinct biochemical profile compared to missense mutations of Noonan syndrome, namely a stronger hyperphosphorylation of ERK, and—to a lesser extent—a phosphorylation of AKT at position T308." (PMID 38969873, 2024). "All three novel RIT1 delins led to a significant increase in ERK phosphorylation, while overexpression of the two Noonan syndrome-associated RIT1 mutations only induced a modest ERK hyperphosphorylation." (PMID 38969873, 2024). "Mutations associated with Noonan syndrome alone include CBL, BRAF, KRAS, LZTR1, MAP2K1 (MEK1), NRAS, PTPN11, RAF1, RIT1, SOS1 and SOS2." (PMID 38550930, 2023). "Consistent with aberrant RAF/MAPK activation as a driver of disease, we show that pathway inhibition alleviates cardiac hypertrophy in a mouse model of RIT1 mutant Noonan syndrome." (PMID 37450595, 2023). "Ras-like-without-CAAX-1 (RIT1), a member of the Ras family of GTPases, has emerged as an important cause of Noonan syndrome and cancer." (PMID 36071839, 2022). "Going further into the signaling cascade, both RIT1 and RAS activate BRAF, heterozygous gain-of-function mutations which result in Noonan syndrome 7 (OMIM: 613706)." (PMID 35806420, 2022). "In two other cases, Noonan syndrome was identified by heterozygous variants in the PTPN11 gene and the RIT1 gene, respectively." (PMID 35160154, 2022). "This is in line with the fact that RIT1 is overrepresented in our cohort of Noonan patients with lymphatic abnormalities (45%), while it only accounts for 6.8% of all cases with Noonan syndrome." (PMID 35778409, 2022). "RIT1’s involvement in Noonan syndrome and lung adenocarcinoma has confirmed its role in the RAS signaling pathway, although the specific mechanism of its function in this pathway has remained elusive." (PMID 34373451, 2021). "For this purpose, we used RIT1, a small GTPase from the Ras family that has recently been involved in the pathogenesis of Noonan syndrome, a neurodevelopmental disorder." (PMID 33410398, 2021). "Case 93 exhibited an NT of 6.0 mm and harbored a heterozygous RIT1 variant (NM_006912.6):c.67A>G (p.Lys23Glu), inherited from the mother, who declined further clinical assessment for Noonan syndrome but showed no overt features." (PMID 41317105, 2025). "Mutations in the following genes that cause Noonan syndrome have been identified: RAS family GTPase proteins (KRAS, NRAS, RIT1, and RRAS), RAS signal function modulators (PTPN11, SOS1, SOS2, CBL, RASA2, and SHOCS2), and downstream signal transducers (RAF1 and BRAF)." (PMID 38248880, 2023). "RIT1 is a RAS guanosine triphosphatase (GTPase) that regulates different aspects of signal transduction and is mutated in lung cancer, leukemia, and in the germline of individuals with Noonan syndrome." (PMID 37450595, 2023). "Further understanding the cellular consequences of oncogenic RIT1 mutations could open up strategies for therapeutic intervention in RIT1-mutant cancers and Noonan syndrome." (PMID 34373451, 2021). "RIT1 (OMIM *609591) was recently reported as a disease gene for Noonan syndrome." (PMID 32396283, 2020). "RIT1, a member of the RAS subfamily, is the latest gene found to be causative of Noonan syndrome." (PMID 32396283, 2020). "Similar cardiac pathologies are found in the severe mouse model of SMA, and one could envision a scenario where severely low levels of SMN promote the accumulation of truncated Rit1, mimicking some Noonan syndrome pathologies." (PMID 27736905, 2016).
Noonan syndrome (continued). "In addition, we verified by exomeanalysis that the patient did not have any pathogenic variants in the genes associatedwith Noonan Syndrome and other rasopathies (PTPN11,SHOC2, KRAS, CBL,SOS1, RAF1, HRAS,NRAS, RASA1, SPRED1,BRAF, MAP2K1, MAP2K2, RIT1 andRRAS)." (PMID 27561113, 2016). "However, all patients had genetically proven Noonan syndrome including patients with a mutation in one of the major genes (RIT1) in which so far no imaging results have been reported." (PMID 35778409, 2022). "In another case series, three infants with Noonan syndrome (SOS1, RIT1, PTPN11) all had a reduction in chylous effusions, chylous ascites, and improvement in respiratory status with trametinib therapy." (PMID 38618951, 2024). "Over the years, several other genes involved in Noonan syndrome (KRAS, SOS1, RAF1, MAP2K1, BRAF, NRAS, RIT1, and LZTR1) have been identified, acting at different levels of the RAS-mitogen-activated protein kinase pathway." (PMID 38254922, 2023). "Eleven patients with Noonan syndrome with lymphatic abnormalities (5 female, 6 male; 7 infants, 4 adults; mean age 10.8 ± 16.4 years) were identified (PTPN11 n = 5/11 [45.5%], RIT1 n = 5/11 [45.5%], KRAS n = 1/11 [9%])." (PMID 35778409, 2022). "Secondary screening confirmed the enhanced sensitivity of RIT1-mutant cells to depletion of USP9X and AURKA along with the RAS pathway and Noonan syndrome genes SHOC2 and SOS1." (PMID 34373451, 2021).
RASopathy (23 papers, 2016 to 2025). Developmental syndromes caused by germline mutations (or in rare cases by somatic mosaicism) in genes that alter the Ras subfamily and mitogen-activated protein kinases that control signal transduction. "The introduction of gain-of-function mutations in RIT1 into zebrafish embryos also causes NS and demonstrates a biological effect similar to mutations in other RASopathy-related genes." (PMID 38672195, 2024). "Many of the RASopathy-associated genes are in gene families: RAF (BRAF and RAF1), RAS (HRAS, KRAS, MRAS, NRAS, RIT1, and RRAS2), MAP2K (MAP2K1 and MAP2K2), and SOS (SOS1 and SOS2)." (PMID 40496714, 2025). "Accumulation of RIT1 through the loss of LZTR1-mediated proteasomal degradation increases MAPK signaling, a defining feature of RASopathies." (PMID 37450595, 2023). "Among these are three RASopathy genes (RAF1, RIT1 and PTPN11), which have been shown to cause isolated LVH in some patients, but have only been comprehensively evaluated in a small number of studies." (PMID 33673806, 2021). "Our data point to a novel aspect in the molecular pathogenesis of RASopathies as we uncovered RIT1 as regulator of cytoskeletal changes through the RHO GTPases RAC1 and CDC42 and their effector PAK1." (PMID 29734338, 2018). "The correlation was the most obvious in the fetus with the RIT1 mutation (case 23), associated with Noonan type 8 (OMIM# 615355): hydrops, ascites and hydrothorax, which were all present in this fetus, are frequent ultrasound markers in RASopathies." (PMID 36900003, 2023). "Similarly, hypertrophic cardiomyopathy occurs in patients with RASopathy, particularly those with germline RAF1 and RIT1 mutations as well as in mouse models carrying mutations in these genes." (PMID 32990679, 2020). "The mean (±SD) number of genes per panel was 33±25, including 8±0.3 sarcomere genes, 4±2 storage cardiomyopathy, and RASopathy genes (LAMP2, PRKAG2, TTR, GLA, PTPN11, RIT1, and RAF1) and 22±23 other genes (range, 0–75)." (PMID 30681346, 2019). "The biochemical relationship between the RASopathy proteins KRAS, RIT1 and LZTR1 was tested in zebrafish and fruit flies; all LZTR1 orthologs preferentially interacted with RIT1 orthologs, indicating that this interaction is also conserved in less-complex model organisms." (PMID 38672195, 2024). "Furthermore, Lztr1R409C/+ mice exhibited splenomegaly and renal hypertrophy, consistent with those found in other RASopathy mouse models, including HRAS p.G12S and RIT1 p.A57G." (PMID 39352760, 2024). "All three of these RAS proteins have been identified as mutated in RASopathies, along with non-canonical RAS proteins, RIT1, MRAS, RRAS, RRAS2 and RALA." (PMID 35103797, 2022). "Our reported proportion may be an underestimate of the true prevalence of RASopathy findings, as earlier versions of the HCM and cardiomyopathy panels utilized in this study did not include the most common of the RASopathy genes associated with left ventricular hypertrophy (PTPN11, RAF1, RIT1)." (PMID 33673806, 2021). "RIT1-CRAF interaction has been frequently proposed due to their critical roles in developmental disorders, collectively called RASopathy, but not directly shown." (PMID 33930461, 2021).
lung adenocarcinoma (11 papers, 2015 to 2025). A carcinoma that arises from the lung and is characterized by the presence of malignant glandular epithelial cells. "RIT1 mutation has a high mutation frequency in some non‐small cell lung cancers (especially lung adenocarcinoma)." (PMID 39833023, 2025). "Mutation in RIT1 has recently been identified in lung adenocarcinomas and RIT1 is proposed to be a driver oncogene in a specific subset of lung adenocarcinomas." (PMID 34625038, 2021). "Analysis of differentially expressed genes in RIT1-mutant and RIT1-amplified lung adenocarcinomas identified significant loss of expression of Hippo pathway genes (FDR = 6e−4)." (PMID 34373451, 2021). "More recently we identified somatic RIT1 mutations in a subset of human lung adenocarcinomas, and found that ectopic expression of mutated RIT1 in cell culture activates Akt signaling and promotes cellular transformation." (PMID 28607354, 2017). "In some malignant tumours such as lung adenocarcinoma, RIT1 mutations appear to be mutually exclusive with mutations in currently known driver genes such as KRAS and EGFR, which suggests that RIT1 may be an independent oncogenic factor in some tumours." (PMID 39833023, 2025). "16% of lung adenocarcinomas harbored mutated or amplified RIT1." (PMID 34373451, 2021). "In a specific subtype of lung adenocarcinomas, RIT1 has been identified as an oncogene driver capable of inducing transformation in NIH3T3 cells through its mutated forms." (PMID 38017479, 2023). "Some genes significantly mutated were exclusively mutated in lung adenocarcinoma, such as STK11 (LKB1), RBM10, KEAP1, RIT1 and MET, while other genes such as NFE2L2, KDM6A, RASA1, NOTCH1 and HRAS are significantly mutated in LSQCC." (PMID 30060526, 2018). "Studies also showed that RIT1 played a critical role in hepatocellular carcinoma, lung adenocarcinoma, myeloid malignancies, and endometrial carcinoma." (PMID 30348939, 2018). "Here, we demonstrated that the loss of LZTR1 could induce the accumulation of RIT1 and KRAS in lung adenocarcinoma cells and promote tumor growth and metastasis." (PMID 37626065, 2023). "LZTR1 deficiency increased RIT1 and KRAS expression in lung adenocarcinoma cells." (PMID 37626065, 2023). "Our analysis of human tumor data showed that over 75% of RIT1-altered lung adenocarcinomas harbor co-occurring loss of expression of at least one Hippo pathway gene, and we verified high rates of YAP1 nuclear staining in an independent RIT1-mutant tumor cohort." (PMID 34373451, 2021). "To investigate whether co-activation of YAP1 and RIT1 occurs in human lung cancer, we analyzed data from 230 human lung adenocarcinomas sequenced by The Cancer Genome Atlas6." (PMID 34373451, 2021). "MutSig can detect RIT1 in lung adenocarcinoma and OBSCN in adrenocortical carcinoma." (PMID 25887147, 2015). "It is worth noting that RIT1 is frequently amplified in various human cancers including HCC, lung adenocarcinoma, cholangiocarcinoma, uterine carcinosarcoma, breast cancer, and ovarian cancer." (PMID 38017479, 2023).
hypertrophic cardiomyopathy (10 papers, 2018 to 2025). A condition in which the myocardium is hypertrophied without an obvious cause. "In a previous study, we generated a novel NS mouse model with a Rit1 p.A57G mutation and demonstrated that Rit1A57G/+ adult mice exhibited hypertrophic cardiomyopathy (HCM) with progressive cell proliferation and fibrosis." (PMID 41388936, 2025). "Patients with RIT1 mutations frequently exhibit cardiovascular abnormalities such as hypertrophic cardiomyopathy and lymphatic disorders." (PMID 41388936, 2025). "Trametinib, a highly selective MEK1/2 inhibitor currently approved for the treatment of cancer, has been shown to reverse left ventricular hypertrophy in two RIT1-mutated newborns with NS and severe hypertrophic cardiomyopathy." (PMID 36140671, 2022). "Exclusion criteria are specific mutations in PTPN1 connected to leukemia and mutations in genes connected to the development of hypertrophic cardiomyopathy (e.g., RIT1)." (PMID 35407641, 2022). "RIT1 mutations are associated with a higher incidence of hypertrophic cardiomyopathy." (PMID 39726952, 2024).